INS (insulin)
Diseases named in the same sentence as INS in open-access papers (continued):
Sharing a sentence is not in itself a finding about the gene and the disease.
acanthosis nigricans (83 papers, 2005 to 2026). A melanotic cutaneous lesion that develops in the axilla and other body folds. "Acanthosis nigricans is thought to develop in obese individuals due to underlying metabolic disruptions resulting in high levels of circulating insulin causing insulin-like growth factor to stimulate proliferation of keratinocytes and dermal fibroblasts." (PMID 38602653, 2025). "The patient is a 6-year-old girl who presented with hypertrichosis, acanthosis nigricans, nephrocalcinosis, and elevated levels of glucose and insulin that served as diagnostic indicators for RMS." (PMID 38542117, 2024). "If a detailed skin examination reveals lesions that are potentially associated with secondary obesity-related diseases, especially acanthosis nigricans, additional diagnostic tests are mandatory (e.g. insulin serum levels, genetic testing)." (PMID 37410088, 2023). "In line with these in vitro findings, a loss-of-function nonsense mutation in the TBC1D4 gene in a severely insulin-resistant Acanthosis nigricans patient was reported." (PMID 24280290, 2013). "Acanthosis nigricans is associated with not only insulin resistance but also insulin hyper secretion." (PMID 21593976, 2008). "The first one targets pancreatic insulin secretion producing its suppression, with the consequent decrease in fat mass (up to 43% when associated with life-style changes) and the reduction of acanthosis nigricans." (PMID 39723164, 2024). "Acanthosis nigricans is an easily identifiable skin lesion, characterized by thickening, hyperpigmentation and accentuation of the skin lines, having a rough and velvety appearance at the affected site and it is associated with insulin resistance." (PMID 31357596, 2019). "Upon clinical presentation, children and youth with T2DM and one or 2 copies of the G319S polymorphism are leaner, have lower insulin levels, greater insulin sensitivity, less acanthosis nigricans, and higher mean haemoglobin A1C than their peers with T2DM but without the G319S polymorphism." (PMID 22288007, 2012). "Additionally, the use of recombinant human IGF-1 (rhIGF-1) was associated with improvements in acanthosis nigricans, and levels of plasma glucose, insulin, fructosamine and HbA1c in patients with extreme insulin resistance syndromes, including congenital generalized lipodystrophy (CGL)." (PMID 40520449, 2025). "The presence of acanthosis nigricans was strongly associated with insulin independence (OR 27.1 [95% CI 7.2, 102.2]; p<0.001); a positive antibody status was associated with a lower likelihood of insulin independence at 12 months (OR 0.10 [95% CI 0.03, 0.36]; p<0.001)." (PMID 38240751, 2024). "Acanthosis nigricans is a clinical diagnosis due to its classical appearance and doesn’t require any biopsy, but further evaluation for insulin resistance can be done." (PMID 40666598, 2025). "A recent exam showed severe acanthosis nigricans around the neck, in the axillae and groin area on both sides, as well as generalized hirsutism and hypertrophy where the insulin pump was inserted." (PMID 41424588, 2025). "In cases of acanthosis nigricans, the presence of hyperpigmented plaques, particularly in intertriginous areas, prompts the assessment of insulin resistance." (PMID 40337376, 2025). "Acanthosis nigricans was present in 93% of the off-insulin group compared with 31% in the on-insulin group (p<0.001)." (PMID 38240751, 2024). "Clues to diagnosis of abdominal obesity–metabolic syndrome include presence of acanthosis nigricans, strong family history, and high insulin requirements (> 1 unit/kg/day)." (PMID 39108603, 2024). "On multivariate analysis, however, only the presence of acanthosis nigricans remained predictive of remaining off insulin." (PMID 38240751, 2024). "The patient we reported had gained 25 kg over five years, had a BMI greater than 28 kg/cm2, and had acanthosis nigricans in the neck and axilla, suggesting possible insulin resistance." (PMID 38334891, 2024).
acanthosis nigricans (continued). "Conditions like acanthosis nigricans, characterized by dark, velvety patches of skin, often signal insulin resistance." (PMID 39407941, 2024). "Another study found that in obese people with acanthosis nigricans, treatment with 3 mg of melatonin per day, for 12 weeks, increased insulin sensitivity and decreased inflammation." (PMID 36337190, 2022). "This study is aimed to observe the effect of laparoscopic sleeve gastrectomy (LSG) on body composition and insulin resistance in Chinese obese patients with acanthosis nigricans." (PMID 29115953, 2017). "Other symptoms included male pattern hair growth, an irregular menstrual cycle, and acanthosis nigricans, all suggestive of insulin resistance, as well as leg cramps after exercise, and burning and tingling sensations in hands and feet." (PMID 28414270, 2017). "The most striking skin manifestation of FPLD 2 is acanthosis nigricans localized around the neck, in axillae and periumbilical area, which is a manifestation of insulin resistance." (PMID 26976018, 2016). "Fasting insulin and HOMA-IR at 21 years were associated with acanthosis nigricans (p = 0.001, both), and those with acanthosis nigricans had higher BMI, WHR and other CVD risk factors." (PMID 25940643, 2015). "The plasma insulin reduction would explain the significant improvement in acanthosis nigricans observed in the two younger children; however, this change did not occur in the older patients despite improved in insulin sensitivity." (PMID 25367549, 2015). "Acanthosis nigricans was found in (70%) of patients resistant to insulin, but it was also present in 54% of patients sensitive to insulin (p = 0.14)." (PMID 18700035, 2008). "Acanthosis nigricans was found in 70% of the insulin resistant group of patients, but it was also present in the 54% of sensitive insulin group." (PMID 18700035, 2008). "Acanthosis nigricans results from long-term exposure of keratinocytes to insulin." (PMID 38957655, 2024). "Resistance to insulin has long been related to acanthosis nigricans." (PMID 38779261, 2024). "She had acanthosis nigricans, impaired fasting glycemia, elevated fasting insulin, and HOMA-IR." (PMID 35095762, 2021). "This difference may be attributed to differences in our samples’ fasting blood glucose and fasting insulin levels, which serve as reflections of insulin resistance, the pathophysiology responsible for acanthosis nigricans and skin tags." (PMID 35103169, 2021). "It was concluded that melatonin could improve cutaneous symptoms in obese patients with acanthosis nigricans by improving insulin sensitivity and inflammatory status." (PMID 29706998, 2018). "Pronounced acanthosis nigricans was observed, being a hint for altered insulin signaling." (PMID 23919306, 2013). "A 45-year-old woman presented with unintended weight loss of 20 kg, unusually widespread acanthosis nigricans, and glucose levels > 500 mg/dL, which could not be controlled with up to 600 IU/d of insulin." (PMID 25675382, 2015). "His two older sisters had been diagnosed with T1DM treated with insulin, and an older sister was diagnosed with T2DM and progressive acanthosis nigricans (Case 6)." (PMID 41424588, 2025). "Studies have noted that patients with acanthosis nigricans exhibit significantly higher fasting insulin levels than their counterparts without the condition." (PMID 40337376, 2025). "Only the presence of acanthosis nigricans remained a useful predictor for not requiring insulin 5 years after diagnosis." (PMID 38240751, 2024). "Predictors of not requiring insulin after 12 months included older age, presence of acanthosis nigricans and the absence of anti-GAD antibodies." (PMID 38240751, 2024). "Acanthosis nigricans screening has been recommended for the assessment, treatment, and prevention of pediatric obesity, in addition to BMI, rather than insulin concentration, which fluctuates during growth." (PMID 35927738, 2023).
acanthosis nigricans (continued). "Therefore, considering that our patient did not present acanthosis nigricans, and laboratory results showed high levels of insulin and anti-insulin antibodies, IAS seems to be the most likely diagnosis." (PMID 30462811, 2018). "In theory, an insulin-induced systemic reduction of IGFBP-1 and IGFBP-2 could increase local levels of free IGF-1, thereby facilitating the development of hyperkeratosis and papillomatosis observed in acanthosis nigricans." (PMID 25977937, 2015). "The strength of these associations was tested in the multivariate model, with only the presence of acanthosis nigricans and the absence of antibodies (anti-GAD or anti-IA-2) remaining significant predictors of being off insulin at 12 months after diagnosis." (PMID 38240751, 2024). "None of the patients had altered glucose levels, and insulin levels and HOMA-IR were elevated in 29.4% and 38.2% of the participants, respectively; 14.7% of the patients exhibited acanthosis nigricans." (PMID 31241662, 2019).
ischemic stroke (79 papers, 2011 to 2025). A stroke disorder caused by obstruction of blood flow to the brain, due to thrombotic (local blood clot formation) or embolic (due to a blood clot or other material traveling from another site) event. "One reason is that the risk of ischaemic stroke increases with lower fasting glucose levels in women than in men, even after adjustment for treatment with oral medication or insulin]." (PMID 40241150, 2025). "Considering these correlations, we subdivided the participants according to age, sex, malignant tumor, previous ischemic stroke, preoperative insulin medication, and surgical category to validate the associations further." (PMID 39838692, 2025). "They found that the reduced Gutt insulin sensitivity index and increased level of two-hour glucose were linked to an increased risk of ischemic stroke." (PMID 39347227, 2024). "The risk of ischemic stroke begins to rise when a woman’s fasting blood sugar level is lower than that of a man, even after adjusting for oral medication or insulin therapy." (PMID 38783249, 2024). "The purpose of our pilot study was to determine whether a combination of neuromuscular electrostimulation (NMES) and insulin therapy could improve the management of T2DM patients with hemiplegia caused by an ischemic stroke." (PMID 33810235, 2021). "Thus, this study aimed to determine whether abdominal adiposity is independently associated with clinical outcomes after ischemic stroke and to elucidate whether this association is mediated by insulin." (PMID 38206990, 2024). "We evaluated the association between the De Ritis ratio and PIS in subgroups of patients stratified by age, sex, malignant tumor, previous ischemic stroke, preoperative insulin medication, and surgical category." (PMID 39838692, 2025). "Hv1 has been implicated in many biological processes, including white blood cell immune responses, sperm capacitation, cancer cell proliferation, tissue damage after ischemic stroke and spinal cord injury, insulin secretion and pain development." (PMID 41316271, 2025). "The associations were consistently maintained in the PSM analysis, sensitivity analysis, and subgroups stratified by age, sex, malignant tumor, previous ischemic stroke, preoperative insulin medication, and surgical category." (PMID 39838692, 2025). "Our previous study demonstrated that insulin action plays an important role in functional outcomes after ischemic stroke." (PMID 38206990, 2024). "Other antidiabetic drugs, such as insulin, have been proven to inhibit the neuronal damage by suppressing elevated glucose levels within 48 h after ischemic stroke." (PMID 37602260, 2023). "In another study, patients with ischemic stroke received intensive insulin therapy or subcutaneous insulin for 24 h." (PMID 37298308, 2023). "The evidence for intranasal insulin administration in protecting neurological function is sufficient, and intranasal insulin administration is a potential therapeutic modality for improving IR and restoring neurological function in ischemic stroke." (PMID 36589857, 2022). "Lifestyle changes, including a healthy diet, weight loss, smoking cessation, and appropriate physical activity are well-known ways to improve peripheral insulin sensitivity and are considered primary prevention of ischemic stroke." (PMID 36589857, 2022). "Insulin, estrogen, progesterone, testosterone, arginine vasopressin, and thyroid hormone have been reported successively in ischemic stroke, which gradually fills the gap of hormones in the field of ischemic stroke research." (PMID 36569944, 2022). "miR-107 is transcribed from the host gene PANK1, which is broadly expressed in many tissues and has been implicated in cancers, chemosensitivity, ischemic stroke, insulin resistance, and neuronal differentiation." (PMID 36059981, 2022).
ischemic stroke (continued). "In summary, there is substantial evidence that insulin sensitizers can boost brain insulin sensitivity, successfully treat ischemic stroke, and improve neurological function." (PMID 36589857, 2022). "As a result, researchers have concentrated on intranasal insulin administration as a neuroprotective treatment for ischemic stroke." (PMID 36589857, 2022). "Despite the fact that there have been few studies on insulin sensitizers in ischemic stroke, we have identified a number of useful insulin sensitizers based on previous research in T2D patients." (PMID 36589857, 2022). "Intranasal insulin administration was shown to have pleiotropic effects during acute, subacute, and chronic phases after acute ischemic stroke events." (PMID 33799976, 2021). "AHSG, a plasma glycoprotein secreted predominantly by the liver, has been associated with atherosclerotic arterial calcifications, insulin resistance, cardiovascular disease, and particularly, ischemic stroke." (PMID 29245986, 2017). "The discovery of lysophospholipids as a common stimulus for Panx1 and Panx2 may underlie the proposed compensatory roles between Panx1 and Panx2 described in ischemic stroke and insulin secretion from β-cells." (PMID 40309905, 2025). "For ischemic stroke, DPP4is, GLP-1 RAs, and glinides were associated with a lower risk (HR: 0.71 [95% CI 0.58–0.87], 0.50 [95% CI 0.32–0.80], and 0.62 [95% CI 0.45–0.84]) compared to insulin." (PMID 40836299, 2025). "In recent years, increasing attention has been given to the relationship between insulin-related indicators, including the TyG index, and ischemic stroke, as glucose and lipid metabolism abnormalities exacerbate cardiovascular and cerebrovascular atherosclerosis." (PMID 40895109, 2025). "Surprisingly, elevated fasting insulin levels did not demonstrate a significant association with ischemic stroke." (PMID 39347227, 2024). "Moreover, it has been shown that apoptosis can be induced by oxidative stress and inflammatory mechanisms triggered by insulin resistance, leading to neurodegenerative diseases such as ischemic stroke and vascular dementia." (PMID 38192426, 2023). "Furthermore, we summarize insulin resistance therapeutic approaches to propose new therapeutic directions for clinically improving prognosis in patients with ischemic stroke." (PMID 36589857, 2022). "In short, AKT is an essential pathway for insulin to exert its physiological effects, and although clinical trials of intranasal insulin administration for ischemic stroke need to be supplemented, the evidence for intranasal insulin administration in protecting neurological function is sufficient." (PMID 36589857, 2022). "Increasing CNS insulin concentrations or CNS insulin sensitivity may be effective not only in preventing ischemic stroke but also in improving the prognosis of ischemic stroke patients." (PMID 36589857, 2022). "However, the risk of ischemic stroke was significantly higher in the TZD group (HR 1.25, 95% CI 1.03–1.50) than the basal insulin group." (PMID 32238842, 2020). "Insulin use was also a significant risk factor in all the three regression models, whereas poor glycemic control was not a significant risk factor for ischemic stroke." (PMID 26989695, 2016). "However, MR research further supports our results that genetically predicted fasting glucose and fasting insulin levels and BMI were not statistically significantly associated with any ischemic stroke subtype." (PMID 33553250, 2020). "However, the increases in insulin might contribute to the appearance of the ischemic stroke subtypes." (PMID 23843789, 2013). "On the other hand, the prevalence of comorbidities including ischaemic stroke/TIA, hemorrhagic stroke and CAD was higher in insulin, sulfonylureas and TZD group than in meglitinides group." (PMID 27513562, 2016).
ischemic stroke (continued). "One of the physiological mechanisms of GPR to predict the 90-day outcome in ischemic stroke patients after EVT is stress, and the RAAS reaction produces excessive catecholamine secretion, elevates serum glucose level to promote secretion of insulin, and carries serum potassium into cells." (PMID 39410992, 2024). "Another study has shown that impaired insulin sensitivity is very prevalent in non-diabetic patients with a recent TIA or non-disabling ischemic stroke." (PMID 36950100, 2023). "Compared with non-diabetic patients, diabetic patients on insulin showed lower creatinine clearance and a more prevalent history of previous ischemic stroke." (PMID 35976428, 2023). "The estimates for haemorrhagic stroke in the insulin treated individuals did however not follow the pattern as for ischaemic stroke, which simply can be explained by the very small number of events in this group." (PMID 34615525, 2021). "Among 241 patients specifically with ischemic stroke, intensive insulin had no clear effect (RR 0.97, 0.83 to 1.14, P = 0.71)." (PMID 23082798, 2012). "Three RCTs involving patients with ischemic stroke used GKI regimens rather than only intensive insulin as their experimental treatment." (PMID 23082798, 2012). "In the most extreme case, insulin therapy was only initiated when glucose levels exceeded 300 mg/dl (16.7 mmol/L), which was, at the time, consistent with AHA Guidelines for the management of ischemic stroke." (PMID 23082798, 2012). "Intensive blood glucose lowering with the use of insulin has failed to provide favorable outcomes in patients with ICH SAH and ischemic stroke." (PMID 30210444, 2018). "The binary logistic regression analysis applied to our data has demonstrated that insulin, PAI-1, and Si levels are independent predictors of the ischemic stroke occurrence, in T2D patients as well as in nondiabetics." (PMID 26089903, 2015). "Therefore, in this study we tried to determine the role of impaired IS, together with the relevant changes in insulin and PAI-1 levels in T2D patients as well as nondiabetics with ischemic stroke." (PMID 26089903, 2015).